AQP4 (aquaporin 4)
Diseases named in the same sentence as AQP4 in open-access papers (continued):
Sharing a sentence is not in itself a finding about the gene and the disease.
bipolar disorder (4 papers, 2021 to 2025). A disorder of the brain that causes unusual shifts in mood, energy, activity levels and the ability to carry out day-to-day tasks. "This suggests a dysregulated expression of AQP4, implicating a potential disruption in brain water homeostasis as a contributing pathogenic mechanism in bipolar disorder." (PMID 40717781, 2025). "It is even possible that AQP4+ EVs may not only be associated with bipolar disorder, but could also play a role in the pathophysiology of other neuropsychiatric diseases." (PMID 40717781, 2025). "The significantly higher levels of mean of AQP4+ EVs in the bipolar disorder group compared to controls raises the question if this could be caused by variation in the regulation of the AQP-4 gene." (PMID 40717781, 2025). "This suggests that AQP4+ EVs may hold potential as a diagnostic or prognostic risk marker for bipolar disorder." (PMID 40717781, 2025). "Recent studies have reported changes of the protein encoded by AQP4 in the cerebellum of patients with bipolar disorder, which may provide novel insights into the pathophysiology mechanisms linked to this condition." (PMID 39727940, 2024). "Our findings revealed significantly more EVs expressing the three AQP4 epitopes in patients with bipolar disorder compared with healthy controls." (PMID 40717781, 2025). "The aim of this study was to investigate the potential role of AQP4 dysfunction in the pathophysiology of bipolar disorder." (PMID 40717781, 2025). "Given the cyclical nature of bipolar disorder, including instances of spontaneous remission in untreated patients, further investigation into the role of AQP4 isomeric EVs in the disease process is warranted." (PMID 40717781, 2025). "They suggested that CSF should be examined to further investigate AQP4-related pathology in patients with bipolar disorders." (PMID 40717781, 2025). "We observed significantly higher levels of EVs expressing AQP4 in the CSF from individuals with bipolar disorder compared with healthy controls." (PMID 40717781, 2025). "This study identified a significant increase in brain-derived EVs expressing AQP4 in the CSF of patients with bipolar disorder, compared to healthy controls." (PMID 40717781, 2025). "The number of EVs expressing AQP4, detected using antigens targeting the three epitopes, was significantly higher in the CSF of bipolar disorder patients compared with the healthy controls." (PMID 40717781, 2025). "To this end, we analyzed the number of AQP4+ EVs in the CSF of a well-characterized cohort of bipolar disorder patients and in the CSF from healthy controls." (PMID 40717781, 2025). "AQP4, a well-known drug target for the treatment of bipolar disorder, was dysregulated in the analyzed datasets included in our study." (PMID 39727940, 2024). "We analyzed exposure of AQP4 EVs to three different epitopes – the N- and C-terminals, and the epitope containing amino acids 273–291 – in CSF by flow cytometry in 24 individuals with bipolar disorder (type 1, n = 20; type 2, n = 4) and in 14 healthy controls." (PMID 40717781, 2025). "In the present study, the aim was to elucidate whether case-control differences in AQP4+ EVs levels in CSF may provide novel insight into the pathophysiology of bipolar disorder." (PMID 40717781, 2025). "Understanding the role and molecular mechanisms of AQP4+EVs could provide novel therapeutic targets, particularly for treatments aimed at restoring blood-brain barrier (BBB) integrity in bipolar disorder." (PMID 40717781, 2025). "VWA8 (von Willebrand domain-containing protein 8), SNAP29 (Synaptosomal-associated protein 29), RIF1 (Replication Timing Regulatory Factor 1), AQP4 (Aquaporin-4) and GSTM3 (Glutathione S-Transferase Mu 3) were some relevant differentially expressed genes detected in the bipolar disorder datasets." (PMID 39727940, 2024).
bipolar disorder (continued). "But contrary to their hypothesis, no AQP4 autoantibodies were detected in the serum from any of their 25 bipolar disorder patients, neither at baseline nor at a follow-up assessment." (PMID 40717781, 2025).
brain inflammation (4 papers, 2011 to 2025). "By improving AQP4 polarization and glymphatic function, hybrid electro‐optical stimulation enhances the clearance of harmful substances and reduces brain inflammation." (PMID 39927473, 2025). "In animal models, intraperitoneal injection of AQP4-IgG in the context of T cell-mediated brain inflammation or intracerebral co-injection of AQP4-IgG and complement induced NMO-like lesions." (PMID 27193196, 2016).
ependymoma (4 papers, 2015 to 2025). A WHO grade II, slow growing tumor of children and young adults, usually located intraventricularly. "Furthermore, our study detected aberrant AQP4 expression in adult spinal ependymomas." (PMID 41160379, 2025).
gastritis (4 papers, 2016 to 2025). Inflammation of the stomach. "For example, there is a relationship between the altered human AQP3 and AQP4 mRNA expression and gastritis types." (PMID 30336596, 2018). "In addition, a correlation between AQP3/AQP4 expression and gastritis types was proposed." (PMID 27589719, 2016). "Collectively, these results indicate that the expression of several subtypes of AQPs (AQP1, AQP3, AQP4, AQP5, AQP7 and AQP11) is upregulated by gastritis, and more studies are essential to investigate their potentials as diagnostic biomarkers and drug targets for gastritis therapy." (PMID 27589719, 2016).
Leber hereditary optic neuropathy (4 papers, 2011 to 2025). Leber's hereditary optic neuropathy (LHON) is a mitochondrial neurodegenerative disease affecting the optic nerve and often characterized by sudden vision loss in young adult carriers. "Screening for autoimmune optic neuritis including testing for anti-myelin oligodendrocyte glycoprotein and aquaporin-4 antibodies and analysis of mitochondrial DNA mutations associated with Leber hereditary optic neuropathy yielded unremarkable results." (PMID 36254071, 2022). "The patient tested negative for aquaporin-4 and myelin oligodendrocyte glycoprotein antibodies and Leber hereditary optic neuropathy-associated gene mutations." (PMID 36254071, 2022).
metastatic tumors (4 papers, 2018 to 2022). "Based on this, we suggest that, similarly, the ADC of metastatic tumors may also reflect AQP4 expression." (PMID 34722268, 2021). "Particularly in cases of peritumoral edema, AQP-4 was highly expressed in brain tissue around metastatic tumors of the brain, not in metastatic tumors." (PMID 31931731, 2020).
myocarditis (4 papers, 2017 to 2023). Myocarditis is a condition that is characterized by inflammation of the heart muscle (myocardium). "Second, AQP4, VSNL1, GABRA4, and GABRB1 were still among the hub genes obtained by subgroup analysis, indicating that these genes were strongly associated with dilated cardiomyopathy caused by myocarditis." (PMID 36286305, 2022).
ovarian teratoma (4 papers, 2022 to 2025). A non-seminomatous germ cell tumor arising from the ovary. "Associated with AQP4 ab and NMDA ab.Concomitant ovarian teratoma." (PMID 37483456, 2023). "The co-occurrence of GFAP-IgG, AQP4-IgG, and NMDAR-IgG is a strong predictor of ovarian teratoma." (PMID 40777035, 2025).
pneumococcal meningitis (4 papers, 2012 to 2025). An acute purulent infection of the meninges and subarachnoid space caused by Streptococcus pneumoniae, most prevalent in children and adults over the age of 60. "This misplacement of AQP4 water channels is likely the cause of the interruption of exchange between the CSF and the brain interstitial space during pneumococcal meningitis." (PMID 36036510, 2022). "Somewhat surprising given the observations of Generoso and colleagues, AQP4 deficiency has been reported to be protective in experimental pneumococcal meningitis, by dramatically reducing brain swelling and the rise in intracranial pressure, thus improving disease outcome." (PMID 36286550, 2022). "Significantly, what affects the solute transport of the glymphatic system during pneumococcal meningitis is not the altered AQP4 expression, but rather the disruption of the AQP4 water channels due to a detachment of the astrocytic end feet from the BBB." (PMID 36036510, 2022). "It was recently reported that AQP4 levels are not altered in the brain's cerebral cortex during pneumococcal meningitis." (PMID 36036510, 2022).
Polyuria (4 papers, 2018 to 2025). An increased rate of urine production. "Collectively, our findings demonstrate that UA reduces the expression of AQP2, AQP3 and AQP4 in an NFκB-dependent manner, which contributes to the polyuria phenotype in subjects with HUA." (PMID 40271210, 2025). "Our findings demonstrate that UA reduces the expression of AQP2, AQP3 and AQP4 in an NFκB-dependent manner, which contributes to the polyuria phenotype in the subjects with HUA." (PMID 40271210, 2025). "Therefore, we infer that the polyuria phenotype of 1alpha (OH) enzyme knockout mice can be partially attributed to reduced water resorption through decreased AQP-4 expression in renal tubules." (PMID 30809535, 2019). "In conclusion, we report that HUA can damage urine concentration capacity leading to a polyuria phenotype via down-regulating AQP2, AQP3 and AQP4 expression in the kidney." (PMID 40271210, 2025). "We revealed that patients and mice with HUA had a polyuria phenotype and found that the expression of aquaporin 2 (AQP2), AQP3 and AQP4 were significantly reduced in the kidneys of mice with HUA." (PMID 40271210, 2025).
prion disease (4 papers, 2008 to 2025). A transmissible disease that is caused by a protein that is able to induce abnormal folding of normal cellular proteins, leading to characteristic spongiform brain changes, which are associated with neuronal loss without an inflammatory response. "In prion diseases, the perivascular waste-clearing system has been observed to upregulate the key protein of the glymphatic system, aquaporin-4 (AQP4), suggesting the therapeutic potential of the glymphatic system." (PMID 40247424, 2025). "In the current work, upregulation of AQP4 ranged from ~ 1.5- to fourfold, an observation consistent with the previously reported increase in expression levels of AQP4 in prion diseases of animals and humans." (PMID 33980286, 2021). "Abnormal increases of AQP1 and AQP4 in the brains of different prion diseases have also described, e.g., the patients of CJD and BSE-infected transgenic mice." (PMID 31814527, 2019).
protein misfolding diseases (4 papers, 2021 to 2023). "Aquaporin-4 (AQP4), a water channel located in the endfeet of astrocyte membrane, is considered a primary driver of the glymphatic clearance system, and defective AQP4-mediated glymphatic drainage has been linked to proteinopathies." (PMID 36140362, 2022).
retinal degeneration (4 papers, 2014 to 2024). Degeneration of the retina. "In this study, we investigated the retinopathy caused by Aβ in AD patients or 5×FAD mice, elucidating the role of the AQP4-mediated ocular glymphatic system in the retinal degeneration induced by brain-derived Aβ." (PMID 39316084, 2024). "In conclusion, understanding the chronic effects of AQP4-IgG on the retina could help unravel the mechanisms behind relapse-independent progressive retinal degeneration of the GCIP." (PMID 37754247, 2023). "However, recent studies have demonstrated that AQP4-IgG can bind to both human and rodent retinas in vivo and ex vivo, resulting in retinal degeneration independent of optic nerve inflammation, suggesting the possibility of a primary retinopathy." (PMID 37754247, 2023).
rheumatic diseases (4 papers, 2018 to 2024). "The current five-fold increased risk of SIEs in AQP4+ patients, compared to the MOG+ group, may likely partly be related to co-morbid rheumatic disease, and associated treatments, which was absent in MOG+ patients." (PMID 38256489, 2024).
spinal cord injury (4 papers, 2017 to 2019). Penetrating and non-penetrating injuries to the spinal cord resulting from traumatic external forces (e.g., WOUNDS, GUNSHOT; WHIPLASH INJURIES; etc.). "Related to spinal cord injury (SCI) lentivirus-based RNAi has been applied for targeting Aquaporin-4 (AQP4), a water channel protein playing a key role the pathophysiological process of SCI." (PMID 30832256, 2019).
thyroid cancer (4 papers, 2012 to 2022). "Similar findings of thyroid cancer expressing AQP4 were reported in a patient with thyroid cancer, predating the onset of NMOSD." (PMID 29064441, 2017). "We examined mRNA expression profiles of AQP3 and AQP4 in eight thyroid carcinoma cell lines using RT-PCR." (PMID 22808259, 2012). "Thus, we examined the expression of AQP3 and AQP4 in normal, hyperplastic and neoplastic thyroid tissues in conjunction with human thyroid cancer cell lines." (PMID 22808259, 2012). "In thyroid cancer cell lines, using RT-PCR and western blotting, AQP3 mRNA and protein were only identified in the TT cell line (human medullary carcinoma cell line) and AQP4 in the other cell lines." (PMID 22808259, 2012).
viral infection (4 papers, 2008 to 2025). "Varicella zoster virus is the most common viral infection involved, though the linkage with anti-aquaporin-4 antibodies is so far unknown." (PMID 32373365, 2020). "Pathology associated with bacterial or viral infections can target organs/tissues that express AQP4 and thus prime AQP4-reactive B cells if they are not clonally deleted or anergized during tolerance induction." (PMID 18510734, 2008). "Certain viral infections, such as Epstein-Barr virus (EBV), are known to induce the expression of both GFAP and AQP4 antibodies." (PMID 40688088, 2025). "Of note, the expression of the major water channel in astrocytes, aquaporin-4 (AQP4), was strikingly inhibited following viral infection." (PMID 36314791, 2022).
abscess (3 papers, 2019 to 2025). An inflammatory process characterized by the accumulation of pus within a newly formed tissue cavity which is the result of a bacterial, fungal, or parasitic infection or the presence of a foreign body. "In conclusion, several lines of evidence in our study indicated that scedosporiosis-induced brain oedema associated with abscess was caused by severe responses of host inflammatory reaction and the increment of intracranial pressure from abscess mass under inappropriate AQP-4 and Nrf-2 responses." (PMID 31080825, 2019). "Therefore, in vivo model of scedosporiosis was conducted in the present study, to investigate the role of AQP-4 and Nrf-2 in the brain oedema-associated abscess using histopathological, immunohistochemical, and electron microscopic studies." (PMID 31080825, 2019). "AQP4 protection probably takes the form of fluid reabsorption from the brain tissue around the abscess and the consequent attenuation of vasogenic edema." (PMID 35910247, 2022). "Increased AQP4 expression was found in the capsule surrounding the abscess." (PMID 35910247, 2022).
acute liver failure (3 papers, 2019 to 2024). Rapid deterioration of liver function causing encephalopathy and coagulopathy. "One study found that AQP4 expression was significantly increased in the brains of rats with acute liver failure, which is a common cause of HE." (PMID 37528089, 2023). "Collectively, diacerein ameliorated cerebral edema and maintained BBB integrity via modulation of TLR4/AQP4/MMP-9 axis thus may decrease the progression of HE induced in acute liver failure." (PMID 39556255, 2024).
brain glioma (3 papers, 2012 to 2024). A malignant glioma that involves the brain. "In recent years, a specific AQP4 inhibitor has been tested in rodents and human brain glioma to directly measure water efflux rate during tumorigeneses." (PMID 38476871, 2024). "Former western blot investigations of aquaporin 4 in glioblastoma tissues and rat brain gliomas always yielded the same results: the AQP4-M23 bands were thicker than the M1 bands independent of the formation of OAPs in the appropriate membranes." (PMID 27483250, 2016). "Western blot analyses showed that these brain gliomas expressed AQP4 isoform -M1 and -M23, like normal rat brain, whereas cultivated cell lines were negative for AQP4." (PMID 22590566, 2012).
CADASIL (3 papers, 2023 to 2025). "We thus infer that at early stage of CADASIL, it is diminished AQP4 protein level rather than impaired AQP4 polarization that contributes to the retarded glymphatic functions." (PMID 39853935, 2025).
cerebral small vessel disease (3 papers, 2022). Cerebral small vessel disease is the term currently used to pathological processes that affect the brain parenchymal circulation (arterioles, capillaries, and veins). "Previous studies have shown the glymphatic clearance function depends on the highly selective expression of AQP4 in microvascular end-feet of astrocytes in the aging brain, traumatic brain injury, and animal models of cerebral small vessel disease." (PMID 35370910, 2022).
cervical cancer (3 papers, 2012 to 2025). A primary or metastatic malignant neoplasm involving the cervix. "Underexpression of AQPs for AQP8 has been observed in colorectal cancer, AQP8 and AQP9 in hepatocellular carcinoma, AQP4 in pleural mesothelioma, and AQP1 in cervical cancer." (PMID 40100646, 2025).
channelopathy (3 papers, 2011 to 2021). Channelopathies are a group of diseases caused by the dysfunction of ion channel subunits or their interacting proteins. "Anti-AQP4-IgG is therefore thought to play a key or even causal role in disease pathogenesis, characterizing the anti-AQP4-IgG positive subset of NMOSD as a channelopathy." (PMID 33776892, 2021). "This low rate is somewhat a paradox that may neglect the role of aquaporin 4 channelopathy or maybe due to incorrect laboratory findings." (PMID 30210729, 2018). "MOG is not a target antigen in "AQP4 channelopathies", raising the question of whether MOG-IgG positive NMO and HR-NMO patients share a possible disease overlap with MOG-IgG positive ADEM." (PMID 22204662, 2011).
CNS demyelination (3 papers, 2022 to 2025). A loss of myelin from nerve fibers in the central nervous system. "The findings suggest that MOG-IgA may be a novel diagnostic biomarker in a distinct subgroup of AQP4-/MOG-IgG double-seronegative patients with CNS demyelination." (PMID 37548987, 2023). "In this study, MOG-specific IgA was identified in a subgroup of patients who were double-seronegative for AQP4-/MOG-IgG, suggesting that MOG-IgA may be a novel diagnostic biomarker for patients with CNS demyelination." (PMID 37548987, 2023).
colon cancer (3 papers, 2020 to 2026). "Next, we investigated the underlying mechanism of AQP4 and SNAP25 in colon cancer by GSEA, and found that the high expression of SNAP25 might be involved in cancer-related signaling pathway, immunity and metabolism processes." (PMID 33150073, 2020). "qRT-PCR results revealed that AQP4 and SNAP25 were significantly elevated in colon cancer tissues compared with adjacent normal tissues (P = 0.003, 0.001)." (PMID 33150073, 2020). "Interestingly, the mRNA relative expression levels of both AQP4 and SNAP25 were significantly elevated in colon cancer tissues compared with adjacent normal tissues (P = 0.003, 0.001)." (PMID 33150073, 2020).
cyst (3 papers, 2019 to 2023). A sac-like closed membranous structure that may be empty or contain fluid or amorphous material. "This study investigated the expression of AQP4 around a mature cyst (syrinx) and the effect of pharmacomodulation of AQP4 on syrinx size." (PMID 37316571, 2023). "Nesic and colleagues suggested that increased AQP4 expression in the spinal cord following injury may lead to edema and swelling and this may contribute, at least in part, to initial cyst formation." (PMID 30909935, 2019).